KIR3DL1 (killer cell immunoglobulin like receptor, three Ig domains and long cytoplasmic tail 1)
Diseases named in the same sentence as KIR3DL1 in open-access papers (continued):
Sharing a sentence is not in itself a finding about the gene and the disease.
KIR3DL1 also shares sentences with these, for which no sentence is quoted: follicular lymphoma (2 papers); myelodysplastic syndrome (2); non-small cell lung carcinoma (2); -LGL leukemia (1); acute lymphoblastic leukemia (1); Alcoholic Cirrhosis (1); aneurysm (1); breast carcinoma (1); Burkitt lymphoma (1); cerebral malaria (1); coronary heart disease (1); diarrheal disease (1); encephalitis (1); gastric cancer (1); Hypertension (1); immune disorders (1); ischemic stroke (1); kidney disease (1); kidney failure (1); liver failure (1); lupus (1); lymphoid leukemia (1); lymphoid neoplasm (1); lymphoma (1); metastatic colorectal cancer (1); neurological disease (1); non-melanoma skin carcinoma (1); Obesity (1); Opportunistic infection (1); ovarian carcinoma (1).
A further 10 diseases each share a sentence with KIR3DL1 in 1 paper.